IL4 (interleukin 4)
Diseases named in the same sentence as IL4 in open-access papers (continued):
Sharing a sentence is not in itself a finding about the gene and the disease.
inflammation (138 papers, 1995 to 2026). Aberrant reaction of the microcirculation characterized by movement of fluid and leukocytes from the blood into extravascular tissues. "Experimental depletion of Vγ1+ cells in an animal CRS model reduced eosinophilic inflammation and suppressed T2-associated cytokines (IL-4, IL-5, and IL-13) and GATA3 expression, indicating that defined γδ subsets can potentiate T2-biased inflammation." (PMID 41470145, 2025). "FB1, as a toxic stimulate factor, can trigger abnormal expression of TNF-α and inflammatory factors, including IL-1β (Interleukin-1 bata), IL-2 (Interleukin-2), IL-4 (Interleukin-4), and IL-10 (Interleukin-10), and cause intestinal inflammation in mice." (PMID 38769285, 2024). "Using a rodent VAP model, we recently showed that MV-induced lung inflammation caused elevated IL-4 secretion and M2 macrophage polarization with reduced bacterial phagocytic capacity." (PMID 31614857, 2019). "Allergic asthmatic inflammation is known to be caused by the secretion of a series of Th2 cytokines (IL-4, IL-5, and IL-13) and proinflammatory cytokines (TNF-α and IL-1β)." (PMID 24312355, 2013). "The other group of cytokines associated with acute eosinophilic inflammation was IL-4 and IL-7." (PMID 35387066, 2021). "The results of this study provide further insight into the kinetics of cytokine expression in allergen-challenged airways, and for the first time in a large animal model demonstrate a Th2 polarized cytokine profile featuring IL-4 and IL-13 associated with allergen-induced airway inflammation." (PMID 26362930, 2015). "Our previous work revealed that conditional PKCλ/ι knockout in CD4+ T cells alleviates S. japonicum-induced hepatic granulomatous inflammation and fibrosis by suppressing Th2 polarization and IL-4+ CD4+ T-cell expansion." (PMID 41154658, 2025). "Studies found that altered flora in patients with neonatal necrotizing small bowel colitis led to significant intestinal inflammation, resulting in increased expression of IL‐1, IL‐2, IL‐4, IL‐6, IL‐8, IL‐10, TNF‐α, IFN‐γ, and IL‐17 in samples." (PMID 40119640, 2025). "The high expression of IL-4 can inhibit inflammatory response, thereby reducing pulmonary inflammation in children." (PMID 41200114, 2025). "The third metabolite tested, 1‐MNA, also has been suggested to be anti‐inflammatory, exerting a hepatoprotective effect in liver inflammation by suppressing IL‐4 and TNF‐α immune cell signaling." (PMID 39989432, 2025). "The results indicated that both treatments significantly reduced the number of CD4+CD44+ T cells, most of which were memory T cells, in addition to reducing lung inflammation and lower levels of Th2 cytokines, such as IL-4, IL-5, and IL-13." (PMID 39060348, 2024). "While increased AHR, lung inflammation and Il-4 production by iNKT cells were observed in PD-L2-/-mice, PD-L1-/- mice showed decreased AHR and lung inflammation and increased secretion of IFN-Y by NK cells." (PMID 36865540, 2023). "Because IL-4 and IL-5 are representative Th2 cytokines that initiate chronic airway inflammation, we further investigated the levels of these cytokines in the lungs." (PMID 37107297, 2023). "Several biologics have demonstrated therapeutic potential for the treatment of this pathology in which IL-4, IL-5 and IL-13 represent the major cytokines involved in the control of eosinophilic respiratory inflammation." (PMID 37763171, 2023). "Prior work has shown that expression of cathelicidin and β-defensin AMPs is decreased by the action of Th2 cytokines such as IL-4 and IL-13.10–12 However, the skin during Th2 inflammation still has a partial increase in host defense gene expression." (PMID 37167061, 2023). "As a typical anti-inflammatory cytokine, IL-4 can reduce the secreta of IL-17 and inhibit synovial inflammation and bone damage." (PMID 35002715, 2021).
inflammation (continued). "The literature describes that IL-10 has an important role in controlling the magnitude of pulmonary inflammation, as it regulates the production of IL-4 and IL-5 by Th2 lymphocytes, in addition to regulation of mast cell-mediated IgE activation." (PMID 35185864, 2021). "Safranal has demonstrated anti-inflammatory effects on OVA-induced airway inflammation via modulation of type 1 and 2 helper T lymphocytes balance, evident from the reduced serum IL-4 and elevated IFNγ." (PMID 33324206, 2020). "Many proinflammatory cytokines (COX-2, iNOS, IL-12, and IL-17) and an anti-inflammatory cytokine (IL-4) are involved in the initiation and development of intestinal inflammation." (PMID 33354574, 2020). "IL-4 and IL-10, Th2-type cytokines, also have been identified as an important mediator of lung inflammation in COPD." (PMID 33281913, 2020). "Some literatures show that LYN in allergic airway inflammation can reduce inflammatory cell infiltration and levels of IL-13 and IL-4 and downregulate allergen-induced airway inflammation." (PMID 33215029, 2020). "Since gut microbiota has been shown to mediate systemic chronic inflammation in various diseases, we next analyzed potential correlations between the differentially abundant fecal microbiota and the inflammatory factors IL-4, IL-6, and IL-10." (PMID 31245306, 2019). "Using house dust mite (HDM)-induced airway inflammation as a model, we confirmed that the in vivo suppressive activity of RbLoTem cells was lost in IL-4-ablated RbLoTem cells." (PMID 31120919, 2019). "The pulmonary inflammation in rat offspring were exacerbated when pregnant or lactating rats were exposed to DEHP with the increased inflammatory factor IL-4." (PMID 31297340, 2019). "We found that the chronic eosinophilic sinonasal inflammation and type 2 immune response, including the production of IL-4, IL-5, IL-13, and CCL11, were less severe in Ifnar1−/− mice than in the WT mice." (PMID 30455684, 2018). "IL-4, IL-10 and IL-13, as the classic anti-inflammatory cytokines, can decrease the production of inflammatory cytokines, and thus inhibit synovial inflammation and bone damage." (PMID 28056922, 2017). "Laboratory study has found that natural moxibustion treatment can reduce IgE and interleukin (IL)-4 levels in the plasma of asthmatic rats, as well as airway inflammation." (PMID 27189087, 2016). "ILC2 responses in the lung can be enhanced by basophils, which produce IL-4 in mouse models of protease allergen-induced airway inflammation." (PMID 27547445, 2016). "Since G-1 attenuated OVA-induced lung inflammation, we measured levels of Th1 and Th2 cytokines (IL-4, 5, and 13 and INF-γ) and an eosinophil-driving chemokine eotaxin (CCL11) in BAL fluid using ELISA." (PMID 25826377, 2015). "Consistent with BML-111-induced downregulation of the TLR2/MyD88/NF-κB pathway, the OVA-induced airway inflammation was restrained, as shown by the reduced serum levels of IL-1β, IL-4 and IL-8, as well as BALF levels of IL-1β, IL-4, IL-8, OVA-IgE." (PMID 25760938, 2015). "Previous reports demonstrated that the levels of pro-inflammatory cytokines, IL-4, IL-5, and IL-13, and airway inflammation were suppressed in mice pre-treated with SCGB1A1 or SCGB3A2 in the OVA-induced allergic airway inflammation model." (PMID 26559674, 2015). "In-vivo allergen-induced airway inflammation study reported that overexpression of LAT prevented the development of airway inflammation with pronouncing reduction of inflammatory cells and IL-4 in BALF." (PMID 23360572, 2013). "IL-4 is the IgE regulator with the highest biological effect known to date, and IL-12 inhibits the activation of mast cells by reducing the production of IL-4, thereby reducing chronic airway inflammation." (PMID 40953067, 2025). "In addition, EVs from hypoxia-conditioned MSCs have been reported to suppress IL-4 and IL-13-driven airway inflammation through the delivery of anti-inflammatory molecular cargo, including miR-146a-5p." (PMID 41465563, 2025).
inflammation (continued). "Cytokines released by Th2 cells, such as IL-4, IL-5, and IL-13, promote the proliferation and activation of eosinophils, mast cells, and goblet cells in the airways, triggering and exacerbating airway inflammation." (PMID 40993641, 2025). "The result of the OVA-induced airway inflammation model shows that Th2 suppression in BALF evaluating IL-4 and IL-5 cytokine production both in preventive and therapeutic administration is possible by delivering an antigen to the cell surface by mRNA-LNP technology." (PMID 41007857, 2025). "Collectively, Pre-F+G VLP immunization induced high titers of neutralizing antibodies, decreased pulmonary inflammation, reduced eosinophil influx, and enhanced IL-4-producing CD4+ T cells, all of which contributed to inhibiting viral replication in the lungs of mice." (PMID 36986643, 2023). "IL-4-producing CD4+ T cell induction following antigen-dependent T cell priming can significantly influence the development of airway inflammation and hypersensitivity and this, combined with activated inflammatory cells and eosinophils, can cause complex pathologies in an autocrine manner." (PMID 36986643, 2023). "Because Th2 cells are dominant sources of IL-4 in lung inflammation, Th2 cell-derived IL-4 may be important for stimulating IL-10 production by ILC2." (PMID 37947634, 2023). "For example, multiple participants may have been afflicted with chronic muscle and bone inflammation, which could be inferred by reduced levels of IL-4 and IL-10." (PMID 35574470, 2022). "An experimental model showed that reducing central cytokines IL-4 and IL-13 could control gut inflammation through the type 2 proinflammatory pathway of the gut mucosa." (PMID 36101343, 2022). "IL-4 upregulates histone demethylase-dependent chromatin modifications in hepatic macrophages, thereby inhibiting M1-type macrophages, promoting M2-type macrophages, and significantly reducing liver inflammation." (PMID 35484116, 2022). "Three days of exposure to Pb induced severe lung inflammation as evidenced by (a) increased the gene expression of several inflammatory cytokines and mediators such as IL-4, IL-10, iNOS, TNF-α, and TGF-α and (b) inhibited the gene expression of anti-inflammatory markers such as IL-6 and IL-8." (PMID 35482242, 2022). "It has been well documented that IL-4 and IL-5 play critical roles in airway inflammation by mobilising and activating eosinophils, which lead to the release of pro-inflammatory mediators such as major basic protein and cysteinyl leukotrienes, which have the capacity to cause AHR." (PMID 33784348, 2021). "However, CerS2 null mice exhibited a significantly decreased level of IL-4 compared with WT mice during OVA-induced airway inflammation." (PMID 33800208, 2021). "For example, it has been shown that IL-4 and IL-5 are anti-inflammatory in models of bleomycin-induced airway inflammation by regulating T cell and myeloid cell expansion, respectively but the molecular mechanisms are unknown." (PMID 32103153, 2020). "IL-4 is recognized as the dominant cytokine for granuloma development and injection with neutralizing antibodies against IL-4 significantly suppresses splenic cell proliferation and hepatic granulomatous inflammation." (PMID 32132991, 2020). "Furthermore, our data also revealed that the effects of curcumin on OVA-induced airway inflammation and mucus hypersecretion in mice and IL-4-induced overexpression of MCP-1 and MUC5AC in BEAS-2B cells were largely blunted by shRNA-PPARγ." (PMID 31073274, 2019). "With cell-specific consequences of IL-4 signaling, we questioned whether IL-4 could regulate neutrophilic inflammation during acute lung inflammation to promote inflammation resolution and restoration of tissue homeostasis." (PMID 30849228, 2019). "Mice that received Th2 cells secreted IL-4, IL-5 and IL-9 and up-regulated Arg1, Eotaxin (Ccl11) and Gob5 (Clca3) within the lung, characteristic of Th1 or Th2-mediated airway inflammation." (PMID 23825948, 2013).
inflammation (continued). "In our experiments, animals in the aerosol group that did not ingest the antigen displayed intense bronchial eosinophilic infiltration and high eosinophilic peroxidases (EPO) and specific IgE activity; elevated IL-4, CCL-11, and CCL-2 are associated with airway inflammation." (PMID 23724232, 2011). "On the other hand, administration of IL-4 plasmid enhanced the severity of airway inflammation." (PMID 16677403, 2006). "In addition, we constructed an immune inflammation-related PPIN (confidence level >0.4) involving interleukin-4 and interleukin-13 signaling, interleukin-10 signaling, and arachidonic acid metabolism, and calculated the degree, betweenness and closeness of each node in the network." (PMID 36003498, 2022). "However, in animal UTI models, IL-4 appears to protect against bladder inflammation." (PMID 33657181, 2021). "Therefore, the purpose of our current study was to explore whether curcumin could alleviate OVA and IL-4-induced asthmatic airway inflammation and mucus hypersecretion both in vivo and in vitro and its involved signal pathway." (PMID 31073274, 2019). "To obtain evidence that inflammation could promote differentiation of non-classic “TC2” cells in vivo, we first examined if naïve CD8+ T cells from blood of children with idiopathic colitis were able to produce IL-4 under conditions that mimic colonic inflammation." (PMID 29922282, 2018). "IL4 divided from T lymphocytes and mast cells could lead to IgE synthesis and airway inflammation." (PMID 29743896, 2018). "Furthermore, eMOD prevented the development of airway inflammation, as demonstrated by attenuation of bronchoalveolar lavages eosinophil influx, peribronchial inflammatory infiltrate, and mucus secretion in lungs and IL-4 and IL-5 levels in lung cell cultures." (PMID 23844022, 2013). "Consistent with qRT‐PCR results of gene expression, enzyme‐linked immunosorbent assay (ELISA) results also showed that B‐PM treatment decreased the levels of cytokines (IL‐4, IL‐6, and IL‐17A) in BALF of mice with airway inflammation." (PMID 39950864, 2025). "We evaluated the gene-based expression of type 2 cytokines (IL-4, IL-5, and IL-13) and STAT 6, which is a transcription factor that plays a crucial role in the pathogenesis of allergen-induced airway inflammation." (PMID 38790633, 2024). "In this study, LF-N2 significantly inhibited IL-6, increased the levels of IL-4 and IL-10 in serum, and the gene expression of NOS in gastric tissue, thereby inhibiting gastric inflammation and injury." (PMID 35299759, 2022). "The degree of nasal mucosal inflammation in AEO group improved, the levels of immunoglobulin E (IgE), histamine, IL-4, IL-5, IL-17 were decreased, and the level of IFN-γ was increased obviously with EC50 = 2 g/kg." (PMID 32395767, 2020). "After the model of intestinal inflammation was induced, the addition of FDC reduced the secretion of IL-10, IL-4, and TNF-α, indicating that FDC can slightly relieve intestinal inflammation." (PMID 32765533, 2020). "Treating mice with TRX inhibits the development of airway inflammation and the overproduction of macrophage inflammatory protein (MIP)-1, RANTES, IL-4, and IL-5, which are responsible for the development of allergic inflammatory responses." (PMID 30469393, 2018). "The high levels of IL-4 production of PP CD4+ T-cells on day 10 of the EW diet and the moderate intestinal inflammation found in the MLN-ectomized mice suggest that PPs play a role in establishing intestinal inflammation in EW-fed OVA23-3 mice." (PMID 25290461, 2014). "Inhalation of 12.5 or 25 mg/ml ketamine markedly suppressed OVA-provoked airway hyperreactivity (AHR), airway inflammation and airway inflammatory cell infiltration into BALF, and significantly decreased OVA-induced up-regulation of iNOS, IL-4 and NO." (PMID 17480224, 2007).
inflammation (continued). "In this study, SEB-induced CRS mice demonstrated increased IL-4 mRNA expression and prominent inflammatory cell infiltration in the sinonasal mucosa, indicating that SEB effectively induces a strong type 2 sinonasal inflammation." (PMID 40943061, 2025). "The concentrations of IL-4, 6, TNF-α, and eotaxin in the bronchoalveolar lavage fluid (BALF) decreased over time, and the levels of these inflammation indicators are consistent with the following inflammatory cell data and acute lung inflammation by ZnO NP." (PMID 34941770, 2021). "In the asthmatic mice induced by sensitization and provocation of airway inflammation with OVA, production of IL-4 and IL-5 in the BALF and inflammatory cells such as leukocytes, neutrophils, lymphocytes, monocytes, eosinophils, and basophils were increased, which enhanced AHR." (PMID 30545126, 2018). "Along with the reduced eosinophilic airway inflammation, IL-13 levels in BALF tended to be lower in OLA-pretreated mice and the production of IL-4 and IL-5 was significantly reduced in BP-restimulated lung cells of OLA-pretreated mice compared to sensitised controls." (PMID 27149118, 2016). "The findings that hapten-induced colonic eosinophilic inflammation is critically dependent on ICAM-1 and that IL-4 provoked aggregation of human mast cells by promoting LFA-1/ICAM-1 adhesion molecules may help to explain our current observation." (PMID 27445435, 2016). "IL-4 has emerged as a central target, not only for B cell IgE production, but also in the commitment of both CD4+ and CD8+ T cells to cells with Th2 effector function capable of secreting IL-5 resultlng in eosinophilic inflammation." (PMID 18475645, 1995). "Besides, the correlations between BIRC3 expression and asthmatic eosinophilic/allergic inflammation indicators (FeNO, IgE, and EOS%), pulmonary function (FEV1, FEV1% pred, FVC% pred, and FEV1/FVC), and inflammatory cytokines (IL-4, IL-5, IL-13, IL-25, IL-10, IL-33, and TSLP) were analyzed." (PMID 35287655, 2022). "IL4 and IL5RA are well-characterized cytokines responsible for Th2 cell differentiation and effector function, ADAM19 is involved in airway and vasculature remodeling, and PRG2 and EPX are both eosinophil-related proteins that play key roles in eosinophil-related airway inflammation." (PMID 29692868, 2018). "However, Soy3+DEP promotes AHR and both neutrophilic and eosinophilic pulmonary inflammation, without increasing the levels of IgE, and more importantly without the involvement of IL-4 and IL-13." (PMID 28628664, 2017). "Loss of both IL-4 and IL-5 during OVA-induced airway inflammation did not abolish airway hyperreactivity, which was abolished only after anti-CD4 treatment, suggesting that ST2/IL-33 signaling in CD4 T cells may be critical for efficient antigen-induced airway inflammation." (PMID 28484466, 2017).